CRP (C-reactive protein)
Diseases named in the same sentence as CRP in open-access papers (continued):
Sharing a sentence is not in itself a finding about the gene and the disease.
bacterial infection (continued). "These factors may suggest that the increased CRP levels and WBC counts associated with WPM-ESD were related to bacterial infection through wounds created by ESD." (PMID 40230564, 2025). "CRP demonstrates limited utility in identifying high-risk bacterial infections, particularly Gram-negative bacteremia, in immunocompromised pediatric populations." (PMID 40647525, 2025). "Therefore, this study aims to evaluate the diagnostic utility of CRP, PCT, neutrophil count, and NLR in identifying bacterial infections in patients with advanced NSCLC undergoing chemotherapy." (PMID 41281267, 2025). "CRP's diagnostic advantage lies in its differential elevation patterns: 1) Significantly greater increases in bacterial infections, 2) Minimal-to-absent elevation in most viral cases." (PMID 41308272, 2025). "However, a significant correlation has been established in most studies between CRP levels and the incidence of bacterial infections in patients with DKA." (PMID 39946377, 2025). "In our study, C-reactive protein was elevated and was significantly higher among patients who showed a positive Pneumocystis PCR result; however, the degree of elevation is generally lower compared to that observed in bacterial infections." (PMID 40283650, 2025). "PCT differs from CRP by its greater specificity for bacterial infections." (PMID 40647525, 2025). "The findings indicated that PCT may serve as a superior early biomarker over CRP in predicting bacterial infection in children with febrile neutropenia and acute leukemia." (PMID 40647525, 2025). "CRP is an inflammatory biomarker that responds to bacterial infection." (PMID 39441193, 2024). "Bacterial infection of the body induces the production of a variety of cytokines, chemokines, and acute chronotropic response proteins, such as IL‐6, IL‐10, C‐reactive protein (CRP), and procalcitonin (PCT), by the body's immune cells." (PMID 39692539, 2024). "We also monitored its levels along the course of the acute inflammatory state and compared its gross kinetic profile with that of CRP to estimate whether OPG could be used as discriminating marker for bacterial infections." (PMID 38509997, 2024). "However, elevated total leukocyte counts and neutrophil counts in combination with tests such as procalcitonin (PCT) and C-reactive protein (CRP) are also important predictors of bacterial infection in patients." (PMID 39559703, 2024). "In the same context, if we consider the CRP as the reference index for the diagnosis of a bacterial infection, then for CRP value > 0.5 mg/dl, an OPG level greater than 4.82 pmol/L (Confidence intervals: 4.10–5.53) would be considered specific for detecting a bacterial infection." (PMID 38509997, 2024). "CRP is an acute-phase reactant frequently used to assist in diagnosing bacterial infections." (PMID 39064542, 2024). "Previous studies have shown that CRP is not a gold standard biomarker for the diagnosis of bacterial infections, and there is a risk of misdiagnosis when making decisions based on CRP levels alone." (PMID 39192993, 2024). "C-reactive protein is indicative of bacterial infection in cases where its value is above 40 IU/L." (PMID 39246860, 2024). "In this Group, patients receiving placebo had an increase in CRP in the second week of the treatment period (Days 10–17) that, when combined with the increased incidence of purulent sputum, potentially suggests the presence of a secondary bacterial infection." (PMID 38811970, 2024). "In the present study, the reason for more in-hospital deaths in the Omicron group may be that it included more patients who were older, immunocompromised, or had complicated bacterial infections with elevated CRP or PCT." (PMID 38374034, 2024). "Additionally, the correlation between mtDNA copy numbers bound to red blood cell surfaces in bacterial infection patients with varying CRP concentrations was examined using univariate linear regression." (PMID 40046178, 2024).
bacterial infection (continued). "A prior study has established the effectiveness of CRP concentration as a sensitive and specific predictor of bacterial infection in individuals with concurrent influenza-like illness, highlighting its pivotal role in the diagnostic scenario presented in this report." (PMID 39020267, 2024). "The elevated CRP values of >60 mg dL−1 suggest bacterial infection." (PMID 39081780, 2024). "In addition, IL‐6 is one of the detectable inflammatory cytokines in early serum and plays an important role in the process of bacterial infection, especially in the induction of CRP and fibrinogen synthesis in the liver." (PMID 38577990, 2024). "Similarly, biomarkers, such as C-related protein (CRP) and procalcitonin, have been demonstrated to be safely used for shortening treatment duration in bacterial infections." (PMID 39589427, 2024). "The sensitivity of CRP in detecting a bacterial infection was superior to OPG (67.3% vs 38.3%)." (PMID 38509997, 2024). "Although CRP is a commonly used biomarker in critical illnesses, it is non-specific for bacterial infections; instead, CRP levels increased in most other causes of inflammation." (PMID 38247605, 2024). "Second, CRP apheresis is feasible and safe, in case of concomitant viral or bacterial infection." (PMID 39211771, 2024). "High CRP is one of the symptoms of serious bacterial infection in infants." (PMID 39810804, 2024). "BV outperformed WBC counts, PCT, and CRP in classifying bacterial infections." (PMID 39441193, 2024). "Indeed, NLR and PLR values, along with levels of PCT, and CRP, were significantly higher in patients with bacterial infections compared to those with other pathologies, which is in line with the literature data." (PMID 39296886, 2024). "WBC, ESR and CRP are commonly used indicators of bacterial infection." (PMID 39501383, 2024). "As a result, it has been suggested that IL‐6 cytokines may increase earlier than CRP during bacterial infections and enable early diagnosis." (PMID 38577990, 2024). "However, the sensitivity of CRP in detecting a bacterial infection is superior to OPG (67.3% vs 38.3%)." (PMID 38509997, 2024). "CRP is an acute-phase reactant protein that is highly sensitive to bacterial infections." (PMID 37550622, 2023). "This may indicate the important role of CRP as an activator of the complement system in bacterial infection." (PMID 38585537, 2023). "Commonly used biomarkers such as C-reactive protein (CRP) and procalcitonin aid the diagnostic process, but are often not sensitive enough to rule out bacterial infection." (PMID 36243780, 2023). "PCT is a marker commonly used to indicate bacterial infection and may be more effective than other clinical indicators such as C-reactive protein (CRP) and white blood cell count (WBC)." (PMID 38125571, 2023). "Increased WBC and CRP were thought to indicate a bacterial infection in those case reports." (PMID 37415644, 2023). "Hence, CRP seems to be a convenient and useful biomarker to detect bacterial infection in older patients, especially when other markers are atypical or not present." (PMID 37737163, 2023). "While PCT has been shown to have higher specificity and sensitivity compared to CRP in the diagnosis of bacterial infections, a meta-analysis in 2007 on 18 studies assessed the use of PCT in critically ill patients and showed significant publication bias and heterogeneity of included studies." (PMID 37109763, 2023). "The serum concentration of CRP in healthy patients is below 10 mg/L; however, its level may be elevated during many pathological conditions, such as bacterial infections, as well as malignant diseases, including GC." (PMID 37240178, 2023). "In our longitudinal study, reductions in pro-inflammatory markers (CRP, IL6 and TNFα) and increments in anti-inflammatory markers (IL4) were associated with an improvement in CSDD and MMSE levels in patients recovering from a bacterial infection." (PMID 37762523, 2023).
bacterial infection (continued). "Tilapia CRP also plays a function during bacterial infection." (PMID 37860004, 2023). "The CRP level was higher in the bacterial infection group, but the WBC count was similar." (PMID 37110306, 2023). "To address this issue and support home-visit nurses in detecting the risk of bacterial infections among elderly individuals at home, we have developed a CRP POCT that does not require a dedicated measuring device or power source." (PMID 37510151, 2023). "In addition, the occurrence of the so-called “rebound effect” was observed after discontinuation of immunosuppressive therapy, but the further increase of PCT and CRP in the course of secondary bacterial infections was limited." (PMID 37762882, 2023). "C-reactive protein (CRP) was also higher in bacterial infections with an average of 122.5 mg/L." (PMID 37797039, 2023). "At a cutoff value of 4.7, the MxA/CRP ratio achieved a Se, Sp and a LR- of 84.6% [95% CI 66.5–93.9%], 100% [95% CI 87.1–100%] and 0.15% [95% CI 0.1–0.4] for differentiating viral and bacterial infections." (PMID 36737561, 2023). "However, the diagnostic accuracy of these biomarkers varies between studies where, for example, CRP has a high sensitivity but low specificity for bacterial infections." (PMID 37371198, 2023). "It has also been shown that CRP as a predictor of bacterial infection is comparable in FN cases and in cases without immunosuppression, albeit with a lower specificity in FN; which is why we choose to apply a stricter CRP cut-off with an upper limit > 100 mg/L to rule in bacterial infections." (PMID 37371198, 2023). "Elevated concentrations of IL-1β, IL-6, and TNF-α in children may be correlated with OM; in particular, IL-6, a marker of a bacterial infection, can induce C-reactive protein (CRP) production and appears to play a vital role in inflammation in OM." (PMID 36911197, 2023). "CRP is a constitutively active protein in the hemolymph of the invertebrate phyla Arthropoda, Echinodermata, and Mollusca, whereas in the serum of vertebrates the concentration of CRP increases significantly following bacterial infections or other triggers such environmental toxins." (PMID 37860004, 2023). "However, the indicators such as neutrophil count, PCT and CRP related to bacterial infection in the SBI group were significantly higher than those in the NBI group." (PMID 37455733, 2023). "However, for extremely low birth weight infants < 1000 g, CRP performed poorly: CRP of 1 mg/dL had a sensitivity of 50% to diagnose bacterial infections." (PMID 36517750, 2022). "Indeed we have previously studied retinal small vessel dilatation and CRP levels in a cohort with bacterial infections before and after antibiotic treatment." (PMID 35918491, 2022). "MxA to CRP ratio in differentiation between viral and bacterial infections." (PMID 35080443, 2022). "Finally, we compared the median eCRPv values between viral and bacterial infections among the patients in the iso-CRP groups." (PMID 36477474, 2022). "The rate of CRP decrease was also similar in bacterial vs. non-bacterial infections." (PMID 36517750, 2022). "CRP levels are strong predictors of bacterial infection in pediatric patients and patients with fever of unknown origin, and clinical decision-making based on bedside CRP measures significantly lowered length of hospital stays." (PMID 36458039, 2022). "Taking into account the timing of C-reactive protein (CRP) testing may improve the performance of the test in diagnosing bacterial infections in the neonatal intensive care unit (NICU)." (PMID 36517750, 2022). "Moreover, in intermediate values of CRP (100–150 mg/L) upon admission, in which the differential diagnosis is controversial, high eCRPv is indicative of bacterial infection, eCRPv >4 mg/L/h represents only bacterial patients." (PMID 36477474, 2022).
bacterial infection (continued). "Although high CRP levels were reported to be more associated with bacterial infections, this was not the case in our study as only 9.6% (17/177), 10.3% (3/29), and 11.5% (13/113) of our patients had positive blood, CSF, and urine cultures, respectively." (PMID 35655792, 2022). "CRP is an important inflammatory marker in bacterial infectious diseases." (PMID 35890253, 2022). "The positive detection rate and combined detection rate of serum SAA, PCT and CRP in the non-bacterial infection group were slightly higher than those in the healthy subjects control group, but the difference between the two groups was not statistically significant (p > .05)." (PMID 35775463, 2022). "Hopefully, our data might be beneficial in further study to understand the protective mechanism of fish CRP against bacterial infection." (PMID 36009776, 2022). "Second, we validated the 8-gene signature in two independent cohorts that used only microbiologically confirmed patients in case-control design and did not establish accuracy of the 8-gene signature against current biomarkers of bacterial infection such as CRP and PCT." (PMID 36543117, 2022). "Previous studies have also shown an advantage of procalcitonin in comparison to CRP in bacterial infection diagnosis, and they may provide important perspectives in scoring systems." (PMID 35204585, 2022). "Therefore, in this research, a CRP gene from Nile tilapia was identified, and its roles during bacterial infection were investigated." (PMID 36009776, 2022). "The CRP level traditionally indicates a bacterial infection." (PMID 36649001, 2022). "PCT has a shorter half-life than CRP and rises faster in bacterial infections." (PMID 35208760, 2022). "However, biological elements associating hyperleukocytosis, elevated CRP, and PCT levels, alerted us to the possibility of a systemic bacterial infection." (PMID 34983630, 2022). "In bacterial infections with severe inflammations, CRP level is between 40 and 200 mg/L." (PMID 36536340, 2022). "CRP is an acute-phase protein, one of the non-specific indicators of the acute inflammatory response phase, and is ideal for the early diagnosis of serious bacterial infections." (PMID 35755831, 2022). "Furthermore, the majority of children for whom a bacterial infection was confirmed by microbiology analyses, were also tested positive with the CRP test (85.7%; 42/49)." (PMID 36536340, 2022). "Therefore, we aimed to evaluate the role of presepsin, PCT, and CRP in the early diagnosis of bacterial infections in patients with ACLF, defined according to EASL-CLIF criteria." (PMID 36143057, 2022). "We demonstrated that the added extrapolation of eCRPv instead of solely using the absolute CRP concentration in ED admission blood samples could improve the distinction between viral and bacterial infection." (PMID 36477474, 2022). "Similarly, elevated CRP and procalcitonin levels suggest a possible secondary bacterial infection and are the key indicators of inflammation, as leukocyte count is not a reliable indicator of disease severity in children." (PMID 36497665, 2022). "However, in a cohort of ICU patients, the positive predictive value of procalcitonin > 1.00 ug/L for microbiologically proven secondary bacterial infections was 93%, while for C-reactive protein >50 mg/L and 150 mg/L the rates were 61% and 84%, respectively." (PMID 35203787, 2022). "The results of this meta-analysis confirmed a comparable diagnostic accuracy for PCT testing in patients undergoing HD and having a bacterial infection using the cutoff value of ≥1.5 ng/ml; Moreover, the diagnostic accuracy of PCT was significantly higher than that of CRP." (PMID 35164633, 2022). "In this study, the results of in vivo experiments showed that rGST-On-CRP only provided limited protection against bacterial infection (SR and bacterial burden), and the expression of inflammatory factors, complement, and interferon were induced at the transcriptional level." (PMID 36009776, 2022).
bacterial infection (continued). "Furthermore, in some severe bacterial infections or burns, CRP level can increase above 200 mg/L, after 48 h of the occurrence of an acute event." (PMID 36536340, 2022). "It is increasingly accepted that CRP is a poor marker of bacterial infection." (PMID 34388194, 2021). "CRP is helpful in detecting serious bacterial infections of fever of unknown origin and has been investigated as a predictive risk factor in infectious diseases, with differing outcomes and study populations reflecting all the different results." (PMID 34830626, 2021). "Inclusion into this cohort was selected on the basis of having data on CRP and PCT, and this could bias the cohort in favour of patients at higher risk of bacterial infection." (PMID 34496795, 2021). "Different tools have been evaluated to establish an early diagnosis of bacterial infection through the use of inflammatory response biomarkers such us C-reactive protein (CRP), procalcitonin (PCT), interleukin 6 (IL-6) and more recently, mid-regional pro-adrenomedullin (MR-proADM)." (PMID 34828740, 2021). "As such, CRP is an excellent biomarker of bacterial infections and the acute inflammatory response." (PMID 34925360, 2021). "Point-of-Care C-Reactive Protein (POCCRP) tests are a potential solution to ascertain whether a patient has a bacterial infection and if an antibiotic is appropriate treatment." (PMID 34748558, 2021). "Besides this, the sensitivity and specificity of CRP are high enough to evaluate the condition of bacterial infection in patients with CLDs." (PMID 34571946, 2021). "Moreover, C-reactive protein, an indicator of bacterial infection, was positively correlated with the bacterial taxa." (PMID 34161373, 2021). "An elevation in CRP levels is generally considered as proof of bacterial infection." (PMID 33892752, 2021). "Also, various markers for predicting bacterial infection such as c-reactive protein (CRP) and procalcitonin (PCT) have been introduced." (PMID 33663442, 2021). "Overall, it prompted that the diagnostic value of PCT and CRP was better than that of WBC in bacterial infection, while WBC was not very useful." (PMID 34836530, 2021). "Notably, IL-6 increases correlated strongly with CRP increases, suggesting a probable connection between cytokine overproduction and bacterial infection." (PMID 33672738, 2021). "Inferring from this, PCT and CRP measurement may help identifying patients with secondary bacterial infections and allow a targeted use of antimicrobials thus promoting antibiotic stewardship." (PMID 34021897, 2021). "CRP had the best accuracy in differentiating viral from bacterial infections." (PMID 34574070, 2021). "CRP is also affected by bacterial infections in the internal and external intestine." (PMID 34362299, 2021). "In this study, we found that patient with bacterial infection had a higher serum concentration of PCT, PSPN and CRP as well as in patient who had unknown cause fever." (PMID 34324506, 2021). "In the future, ConnDx could be deployed for bacterial infections if these can be diagnosed by RDTs (e.g. for C Reactive Protein), leading to better-informed antibiotic prescriptions, which is important in fighting antimicrobial resistance." (PMID 34348696, 2021). "In patients presenting with relatively low CRP concentrations but high clinical suspicion of bacterial infection, calculating the rate of rise to first CRP and the dynamics to a second CRP measurement helps in differentiating between bacterial and viral etiologies." (PMID 34863104, 2021). "CRP, as an acute reactant, is produced in bacterial infection or inflammation." (PMID 34035353, 2021). "Whether procalcitonin (PCT) or C-reactive protein (CRP) combined with certain clinical characteristics can better distinguish viral from bacterial infections remains unclear." (PMID 34583675, 2021). "PCT is a better discriminator between viral or bacterial infections compared to CRP." (PMID 34079538, 2021).